LINC00114 (long independently transcribed non-coding RNA 114)
Synonyms: C21orf24; NCRNA00114
Gene: Long non-coding RNA gene on chromosome 21 (38,733,890 to 38,773,501, reverse strand). Ensembl gene ENSG00000223806.
Diseases named in the same sentence as LINC00114 in open-access papers:
LINC00114 is named in the same sentence as 13 diseases in open-access papers, as found by Europe PMC text mining. Sharing a sentence is not in itself a finding about the gene and the disease. The quoted sentences say what the papers report.
colorectal cancer (4 papers, 2020 to 2025). A primary or metastatic malignant neoplasm that affects the colon or rectum. "Additionally, LINC00114 has been shown to play a role in the development of colorectal cancer and esophageal cancer." (PMID 40788820, 2025). "Also, a study has shown that LINC00114 serves as an oncogenic role in colorectal cancer (CRC) via regulating enhancer of zeste homolog 2 (EZH2)-mediated methylation of the target gene." (PMID 35414117, 2022). "LINC00114 could promote the development of colorectal cancer, but its mechanism has been rarely discussed in esophageal cancer (EC)." (PMID 35414117, 2022).
bladder cancer (1 paper, 2022). "Increased expression of LINC00473 in HNSCC; LINC00114, MINCR and PVT1 in NPC; Linc-RA1 in glioma; LINC00473and CYTOR in NSCLC; NEAT1 and LINC00958 in cervical cancer; H19 in cardiac cancer; LINC02582 in breast cancer; and TUG1 in bladder cancer were associated with radioresistance." (PMID 36323697, 2022).
colon cancer (1 paper, 2021). "We find that LINC00114 is associated with OS in colon cancer patients (P = 4.255e−03)." (PMID 33832120, 2021). "We find that LINC00114 and UCA1 are upregulated in colon cancer which to be associated with the early tumor stage." (PMID 33832120, 2021). "In conclusion, LINC00114 has the potential to be a prognostic biomarker and they can be used for early diagnosis of colon cancer." (PMID 33832120, 2021). "The LINC00114/miR-107/PCKS5 axis may plays an important role in colon cancer tumorigenesis and requires further research." (PMID 33832120, 2021). "LINC00114 and UCA1 are confirmed to be associated with the early stages of colon cancer." (PMID 33832120, 2021). "High expression of LINC00114 leads to improved overall survival (OS) in colon cancer patients." (PMID 33832120, 2021). "High expression of LINC00114 can lead to poor overall survival of colon cancer patients." (PMID 33832120, 2021). "The expression of LINC00114 is higher in stage I and UCA1 is lower, indicating that they can be used for early colon cancer diagnosis." (PMID 33832120, 2021). "LINC00114 and UCA1 are both highly expressed in colon cancer tissues compared to normal tissues in the TCGA database." (PMID 33832120, 2021). "In addition, LINC00114 may be involved in the overall survival of colon cancer patients." (PMID 33832120, 2021). "In addition, LINC00114/miR-107/PCSK5, UCA1/miR-107/PCKS5, and UCA1/miR-129-5p/SEMA6A axes may play an important role in colon cancer carcinogenesis and require further research." (PMID 33832120, 2021).
lymph node metastasis (1 paper, 2022). "The expression level of LINC00114 positively correlated with the TNM stage, diameter of the tumor, lymph node metastasis, distant metastasis, and body mass index (BMI)." (PMID 35847359, 2022).
tumor (5 papers, 2019 to 2022). "Tumor formation in nude mice implicated that sh-LINC00114 reduced the tumorigenic ability of Eca109 cells while si-DLC1 had the opposite effect in nude mice." (PMID 35414117, 2022). "In the process of CRC, LINC00114 expression trends to up-regulate, and down-regulating LINC00114 inhibits proliferation in vitro, and retards tumor formation in vivo via reducing EZH2/DNA methyltransferase 1-induced methylation of miR-133b promoter." (PMID 35414117, 2022). "The expression of LINC00114 was downregulated in tumor tissues, metastatic CRC tissues, and stage 4 tissues." (PMID 33302562, 2020). "We also performed a nude mouse xenograft model to explore the effects of LINC00114 in vivo and found that, consistent with the findings above, LINC00114 suppression significantly reduced the tumor growth, compared with the control group." (PMID 31921641, 2019). "We found that LINC00114 was up-regulated in both EC tissues and cells, and silence of LINC00114 repressed proliferation, migration, invasion and glycolysis while induced apoptosis of EC cells in vitro, as well as resulted in suppression of tumor formation in vivo." (PMID 35414117, 2022). "In conclusion, tumor-infiltrating immune cells may affect the clinical consequences of LINC00114/UMODL1 and LINC00114/OIT3 axes in COAD." (PMID 35847359, 2022).
cancer (3 papers, 2019 to 2025). A tumor composed of atypical neoplastic, often pleomorphic cells that invade other tissues. "Overall, LINC00114 is a promoter for cancer development, and suppressing LINC00114 may serve to inhibit tumorigenesis, which may be related to DNA methylation." (PMID 35414117, 2022). "In addition, LINC00114 depletion inhibited cancer cell proliferation both in vitro and in vivo." (PMID 31921641, 2019).
LINC00114 also shares sentences with these, for which no sentence is quoted: esophageal cancer (2 papers); breast carcinoma (1); cervical cancer (1); glioma (1); leukemia (1); nasopharyngeal carcinoma (1); non-small cell lung carcinoma (1).